CBS (cystathionine beta-synthase)
Diseases named in the same sentence as CBS in open-access papers (continued):
Sharing a sentence is not in itself a finding about the gene and the disease.
tumor (continued). "Patients with cfDNA hypomethylation of CBS promoter in plasma were correlated with high tumor stage and poor clinical outcome." (PMID 28881655, 2017). "Then, the DNA methylation level of CBS promoter was further detected in tumor tissues of all 95 patients (41.58% ± 25.86%, median = 37.50%)." (PMID 28881655, 2017). "Most tumor tissues of patients from LTM group (95.92%) showed a moderate/high CBS staining, but less tumor tissues of patients from HTM group (10.87%) showed a moderate/high CBS staining (P < 0.001)." (PMID 28881655, 2017). "In colon cancer, H2S produced by CBS in tumor can stimulate angiogenesis, increase tumor blood flow and ATP generation, resulting in tumor growth." (PMID 29018341, 2017). "Quantitative real-time PCR showed that the mRNA level of CBS was higher in tumor tissues of patients from LF group than from HF group." (PMID 28881655, 2017). "Most tumor tissues of patients from LF group (83.93%) showed a moderate/high CBS staining, but less tumor tissues of patients from HF group (12.82%) showed a moderate/high CBS staining (P < 0.001)." (PMID 28881655, 2017). "In this study, the effect of low RBC folate level (LF group) and hypomethylation of CBS promoter in tumor tissues (LTM group) was very consistent in patients’ classification (Spearman = 0.776, Kappa = 0.767)." (PMID 28881655, 2017). "Our results indicated a cfDNA hypomethylation of CBS promoter in patients and the methylation variation of CBS promoter in plasma cfDNA is strikingly consistent with tumor tissues." (PMID 28881655, 2017). "Quantitative real-time PCR showed that the mRNA level of CBS was significantly higher in tumor tissues of patients from LTM group than from HTM group." (PMID 28881655, 2017). "Even more important, patients with cfDNA hypomethylation of CBS promoter in plasma were correlated well with high tumor stage and poor clinical outcome of CRC." (PMID 28881655, 2017). "Silencing CBS and SREBPs significantly inhibit tumor growth in pre-clinical orthotopic mouse models." (PMID 26452259, 2015). "In orthotopic tumor models, CBS or SREBP silencing resulted in reduced tumor cells proliferation, blood vessels formation and lipid content." (PMID 26452259, 2015). "Stable knockdown of CBS significantly inhibited the tumor growth and the average weight of these tumors was 0.6 g." (PMID 26452259, 2015). "Combination therapy of CBS siRNA and cisplatin resulted in a dramatic (∼90%) reduction in tumor weight compared to the cisplatin only treated group." (PMID 24236104, 2013). "A significant (∼40%) reduction in tumor weight was noted in the CBS siRNA treated group compared to the control siRNA treated group." (PMID 24236104, 2013). "We also investigated the potential role of CBS gene hypermethylation as a biomarker to predict tumor relapse or metastasis in stage II (T3N0M0) CRC patients." (PMID 23152928, 2012). "Correlation of CBS methylation, KRAS mutation and tumor relapse/metastasis status in primary stage II CRC samples." (PMID 23152928, 2012). "CBS can be oncogenic or act as a tumor suppressor, depending on the tumor type." (PMID 39940704, 2025). "Here, we further demonstrated that CBS is highly expressed in KYSE450, NEC, MCF7, A549 and HCT8 cells and downregulation of CBS has been shown to inhibit tumor cell migration and invasion, as well as suppress angiogenesis and lymphangiogenesis in KYSE450, A549 and HCT8 cells." (PMID 38828455, 2024). "The finding that enhanced transsulfuration activity contributes to the exocrine secretion of cysteine in CAFs raises the possibility that stromal CBS may participate in the evasion of PDAC ferroptosis through regulation of the metabolic state of the tumor." (PMID 38389839, 2024).
tumor (continued). "Similarly, Pmel T cells transduced with CBS and adoptively transferred into tumor-bearing mice maintained significantly higher GM130 expression when isolated from the tumors." (PMID 39546607, 2024). "Therefore, further studies on the role of CBS in tumorigenesis must consider tumor type and also grade." (PMID 37483514, 2023). "Silencing of CBS or CSE shows the same tumour‐suppressing effect." (PMID 36929586, 2023). "In HCC cell lines Hep3B and MHCC97H, CBS inhibits tumour growth by regulating apoptosis‐related proteins (cleaved Caspase‐3 and Bcl‐3) and inhibiting the transcription of paired related homeobox 2 by interleukin‐ 6 (IL‐6), which negatively regulates the expression of STAT3." (PMID 36929586, 2023). "In vivo CBS silencing inhibits tumour angiogenesis by reducing Ki67 and CD31." (PMID 36929586, 2023). "There are several molecular mechanisms by which CBS-driven H2S production supports tumor growth, including via maintenance of mitochondrial respiration and ATP synthesis, stimulation of cell proliferation and survival, control of redox balance, and increasing vasodilation." (PMID 36358931, 2022). "Furthermore, it has also been shown that CBS not only promotes tumor growth and progression, but CBS is also involved in tumor formation." (PMID 36088423, 2022). "Cytosolic CBS protein expression level, as measured by the percentage of cells with positive CBS staining, and fluorescence intensity were significantly downregulated in tumor tissues compared to the adjacent normal gastric tissues." (PMID 35758651, 2022). "CBS siRNA and cisplatin, on the other hand, significantly reduced tumor weight and nodules." (PMID 35684331, 2022). "The expression profiles of hub genes other than the CBS gene were positively correlated with drug sensitivity, which may be related to tumour resistance." (PMID 36248799, 2022). "In addition, the function of CBS in liver cancer remains inconclusive with conflicting reports of both tumor-promoting and -suppressive roles." (PMID 35758651, 2022). "Under such circumstances, CBS overexpression and exogenous H2S manifests tumor-suppressing activities in CRC cells, including inhibition of proliferation, decreased clone formation, attenuation of migration, as well as an impaired capacity of in vivo xenograft growth and liver metastasis." (PMID 35172821, 2022). "Moreover, the anti-tumor activity of CBS/H2S axis was largely attributed to the inhibition of a pivotal stem cell marker, CD44." (PMID 35172821, 2022). "SELENBP1 and CBS are reciprocally regulated during spontaneous differentiation of Caco-2 cells to a colonocyte-like phenotype, thus paralleling their opposing regulation in the tumor tissue of CRC patients." (PMID 36290680, 2022). "Therefore, the expression of CBS is significantly altered in several human tumor types, and the expression of CBS has a few characteristics." (PMID 35684331, 2022). "CBS-derived H2S has been identified as a tumor growth factor and anticancer medication target." (PMID 35684331, 2022). "Additionally, the direct injection of AOAA into the xenograft tumor parenchyma reduced peritumor blood flow, while administration of the CBS substrate L-cysteine increased this flow." (PMID 35366284, 2021). "Therefore, it is highly possible that ERK1/2 activities, which can be stimulated by H2S-mediated persulfidation on MEK1, are the key drivers to promote tumor growth in CBS or CTH overexpressing tumors." (PMID 34207284, 2021). "Interestingly, in a study of 21 ccRCC tissue samples compared to benign renal tissues from the same individuals, 66% of the pair samples showed stable CBS expression, with the remaining samples exhibiting suppressed tumor tissue CBS levels." (PMID 35366284, 2021).
tumor (continued). "It implies that besides the intratumoral delivery of therapeutic NO/CO/H2S gases and their prodrugs, the tumor-targeted delivery of related iNOS/HO1/CBS inhibitors by nanomedicine approach also holds great promise to improve anticancer efficacy and avoid side effects." (PMID 34691545, 2020). "The lack of function or suppression of tumor growth by CBS in certain tumor types indicates that CBS associated oncogenesis is tumor-specific." (PMID 30050925, 2018). "CBS not only promotes tumor growth and progression but also initiates tumor formation." (PMID 30050925, 2018). "Diminished CBS levels were also detected in the tumor tissues from the mouse model of HCC." (PMID 30050925, 2018). "Then, all 95 patients were divided into high DNA methylation level group (HTM group, > mean, n = 46) and low methylation level group (LTM group, < mean, n = 49) according to the average DNA methylation level of CBS promoter in all tumor tissues (mean = 41.58%)." (PMID 28881655, 2017). "Inhibition of CBS significantly reduced the growth rate of the tumor xenografts, which might be related to intratumoral mechanisms or paracrine mechanisms in the tumor microenvironment." (PMID 27199771, 2016). "In addition, we determined the total triglyceride and cholesterol content in the tumor specimens and identified a substantial decrease of the biomolecules in CBS and SREBPs knockdown tumors." (PMID 26452259, 2015). "A marked (∼70%) decrease in the number of tumor nodules was observed after treatment with CBS siRNA only and efficacy was further potentiated by combination therapy i.e. CBS siRNA and cisplatin, which showed a decrease of nearly 80% compared to the cisplatin only treated group." (PMID 24236104, 2013). "Therefore, depletion of cyst(e)ine in the tumor microenvironment combined with inhibition of intracellular CBS could be a more potent therapy for CRC." (PMID 38490069, 2024). "Also, suppressing CBS expression led to a reduction in tumor growth." (PMID 37627515, 2023). "Therefore, a key driver of tumor growth in CBS or CTH overexpressing tumors may be the ability of H2S-mediated MEK1 persulfuration to stimulate ERK1/2 activity." (PMID 37895865, 2023). "In addition, overexpression of CBS attenuated tumor growth and liver metastasis in vivo." (PMID 35172821, 2022). "The finding that CH004 increases ROS generation, a finding that was interpreted by the investigators as an indicator of ferroptosis, may be consistent with the regulatory role of CBS in tumor cell ferroptosis; independent studies using CBS silencing are consistent with this conclusion." (PMID 32365821, 2020). "Indeed, CBS inhibition may afford anti-tumor activity and abrogation of chemoresistance via attenuated GSH synthesis and nuclear metallothionein expression." (PMID 31635026, 2019). "CBS may also promote tumor cell survival by increasing cell intrinsic antioxidant capacity." (PMID 30050925, 2018). "Evidence level: preclinical and dominant signals: CBS/CSE/3-MST overexpression, tumor “sulfur addiction”, and xenograft sensitivity to enzyme inhibition (e.g., AOAA) or high-load donors (e.g., GYY4137)." (PMID 41020887, 2025). "To ascertain the translation of the in vitro results to an in vivo model system, we subcutaneously injected CBS KD and control SW480 cells into nude mice and monitored the tumor growth." (PMID 38490069, 2024). "Future studies should investigate the regulation of CBS mRNA by HSF1 in PCa with cysteine levels and culture conditions that mimic the PCa tumor microenvironment." (PMID 38172561, 2024). "CBS KD significantly inhibited the growth of CRC xenografts, as indicated by the reductions in tumor volume and weight." (PMID 38490069, 2024).
tumor (continued). "The results showed that inhibition of stromal CBS (shCBS or AOAA treatment) significantly reduced both the levels of GSH and the ratio of GSH/GSSG in tumor cells with cystine-free medium." (PMID 38389839, 2024). "This showed that the tumor volumes were increased in the cisplatin-treated mice injected with PANC-1 cells and CBS-knockdown CAFs, compared with cisplatin-treated mice injected with CBS-control CAFs." (PMID 38389839, 2024). "Subsequently, the cystine-restricted diet markedly reduced tumor growth, and this reduction was more pronounced in the group treated in combination with AOAA, indicating that depletion of CBS and cystine deprivation synergistically inhibits CRC tumorigenesis." (PMID 38490069, 2024). "In clear cell renal cell carcinoma, either hydroxylamine (HA; a dual inhibitor of CBS and CSE) or PAG exerts tumour‐suppressive effects both in vivo and in vitro." (PMID 36929586, 2023). "The reduction of serine levels has been related to the overexpression of cystathionine β-synthase (CBS), an enzyme that, together with cystathionine λ-lyase (CSE), is involved in the synthesis of GSH and in cell proliferation and tumor growth." (PMID 36914921, 2023). "In terms of grade alone, CBS, CD44, and CHAC1 increased with tumor grade, while HMGCR was decreased." (PMID 35422048, 2022). "With TCGA cohort, we studied endogenous H2S synthetase expressions and, found that CSE/CTH, CBS and MPST expressions were enhanced in tumor tissues comparing with normal samples." (PMID 32195181, 2020). "The results verified that FO consumption inhibited tumor growth by modulating GSSG/GSH level, suppressing CBS protein expression, nucleotide synthesis and reducing energy source (ATP) in a HPAF-II cell- implanted mouse xenograft model." (PMID 33137095, 2020). "Accordingly, in the human colorectal cancer cell line HCT 116, shRNA-mediated silencing of CBS or its pharmacological inhibition by aminooxyacetic acid (AOAA) significantly impaired cellular proliferation and migration, and tumor xenograft growth." (PMID 30679627, 2019). "In this study, the effect of hypomethylation of CBS promoter in tumor tissues (LTM group) and the moderate/high CBS staining was very consistent in patients’ classification (Spearman = 0.854, Kappa = 0.852)." (PMID 28881655, 2017). "The effect of hypomethylation of CBS promoter in cfDNA of patient plasma (LPM group) and in DNA of tumor tissues (LTM group) was very consistent in patients’ classification (Spearman = 0.834, Kappa = 0.831)." (PMID 28881655, 2017). "Benserazide, an inhibitor of CBS, in combination with paclitaxel, decreased SIRT1 sulfhydration and hypoxia-inducible factor 1-alpha/vascular endothelial growth factor (HIF-1α/VEGF) expression in tumor models." (PMID 41465271, 2025). "CBS expression in cutaneous melanoma tissues has been correlated with immune infiltration of CD8+ T cells, response to anti-PD-L1 immunotherapy, tumor microenvironment dynamics, MHC-I antigen presentation pathways, overall survival, tumor immune evasion, redox regulation, and immunotherapy efficacy." (PMID 41373571, 2025). "In addition, both stromal CBS-knockdown and AOAA treatment significantly inhibited tumor proliferation in both PANC-1 and MIAPaCa-2 cells in Erastin/IKE-containing medium, as shown by EdU staining." (PMID 38389839, 2024). "It is important to note that AOAA is also known for its ability to inhibit other critical enzymes involved in tumor progression, such as CTH and GOT, which could significantly complicate the interpretation of effects attributed solely to CBS inhibition." (PMID 39062461, 2024).
tumor (continued). "Silencing CBS increases the expression of angiogenesis inhibitor SERPINF1 and inhibits the expression of Ki67, CD31, CD34, and hypoxia‐inducible factor (HIF‐1α), and reduces GSH synthesis enhanced oxidative stress, thereby inhibiting tumour cell growth." (PMID 36929586, 2023). "CBS, CSE, and MPST are differently expressed in various tissues and organs, but their levels can also be up or downregulated under diverse conditions and in different tumor types." (PMID 37483514, 2023). "Previous studies including our work have validated the upregulation of CBS/H2S in CRC tumor specimens compared with patient-matched nonmalignant tissues." (PMID 35172821, 2022). "We also observe high levels of CBS expression in a proportion of GC cell lines that tend to be non-CIMP, suggesting that CBS gene dosage is a key factor to maintain a normal metabolic state, and its expression distinctly varies with tumor subtype." (PMID 34074348, 2021). "Inhibition of CBS reduced the proliferation of the CML primary bone marrow mononuclear cells and induced growth inhibition, apoptosis, cell cycle arrest, and migration suppression in K562 cells and tumor xenografts." (PMID 33558454, 2021). "Our study demonstrated similar results, showed that consumption of FO increases GSSG/GSH ratio in tumor tissues and effectively inhibits the expression of CBS protein as compared to the non-FO tumor group (control group)." (PMID 33137095, 2020). "Comparatively, the use of aminooxy‐acetic acid (AOAA) as the CBS inhibitor lowered the H2S production and subsequently decreased the conversion of Cu2O into copper sulfide, exhibiting no obvious PA signal in tumor and negligible temperature variation." (PMID 33173728, 2020). "Analysis of 120 HCC specimens found that CBS mRNA was markedly lower in tumor tissues than surrounding noncancerous liver." (PMID 30050925, 2018). "Among all CpG sites that were hypermethylated in tumor samples (data not shown), four CpG sites located were in the CBS gene." (PMID 23152928, 2012). "where pS is the (unknown) proportion of stroma, CAS and CBS are the ASCNs of the stromal cells, and CAT and CBT are the (unknown) ASCNs in the tumor." (PMID 16322765, 2005). "Similarly, when YTHDF2 forms a complex with CBSLR/YTHDF2/CBS, it destabilizes CBS mRNA in an m6A-dependent manner, leading to ACSL4 degradation via the ubiquitin-proteasome pathway and inhibiting ferroptosis in the hypoxic tumor microenvironment." (PMID 40001550, 2025). "Notably, the marked activation of CYP1A1, CYP1B1, and SLC16A6, coupled with the downregulation of tumour suppressors such as LINC01085 and CBS, underscores the potential of PM2.5 to promote oxidative stress, carcinogenesis, and therapy resistance in a mutation-dependent manner." (PMID 40559957, 2025). "CBS is a pyridoxal 50-phosphate (PLP) enzyme that catalyzes the conversion of homocysteine (Hcy) and serine into cysteine by the transsulfuration pathway and regulates the metabolism of hydrogen sulfide (H2S), with higher H2S levels related to the proliferation of multiple tumor types." (PMID 36778917, 2023). "Interestingly, with cisplatin, the siRNA treated mice showed a small and nonsignificant reduction in tumor weight, while the mice treated with CBS siRNA plus cisplatin exhibited a 90% reduction in tumor weight compared to the mice treated with siRNA only." (PMID 35366284, 2021). "The logical follow-up question, therefore, is to determine whether the forced up-regulation of CBS in a non-tumorigenic cell can confer a tumor-like phenotype." (PMID 32365821, 2020). "In contrast with the high potency of CH004 on recombinant CBS and in cultured cells, in the in vivo studies using tumor-bearing mice, the efficacy of the molecule was not particularly impressive: a dose of 10 mg/kg/day partially inhibited the growth of liver tumor xenografts." (PMID 32365821, 2020).